IGFBP2 (insulin like growth factor binding protein 2)
Diseases named in the same sentence as IGFBP2 in open-access papers (continued):
Sharing a sentence is not in itself a finding about the gene and the disease.
gastric cancer (8 papers, 2013 to 2025). A primary or metastatic malignant neoplasm involving the stomach. "Herein, we investigated the diagnostic and prognostic role of circulating IGFBP2 in gastric cancer patients." (PMID 28036255, 2017). "We tested IGFBP2 levels in the sera of 118 gastric cancer patients and 34 healthy controls using enzyme-linked immunosorbent assay (ELISA)." (PMID 28036255, 2017). "To test the diagnostic value of serum IGFBP2, we compared the circulating IGFBP2 levels between gastric cancer patients and healthy controls." (PMID 28036255, 2017). "In this current study, 23 m6A regulators were summarized and it was discovered that compared to normal gastric tissues, 22 m6A regulators except IGFBP2 showed higher expression levels in gastric cancer tissues." (PMID 38206646, 2024). "From a quantitative point of view, IGFBP2 protein expression was lower in gastric cancer tissues compared with in normal tissues (P < 0.001)." (PMID 37088808, 2023). "Based on the results of the qPCR verification and considering the lack of IGFBP2 protein expression data in the Human Protein Atlas (HPA), we performed IHC staining to verify the protein expression of IGFBP2 in gastric cancer tissues." (PMID 37088808, 2023). "Multivariate analysis showed that only higher N stage (N2/3) (HR: 2.858, P = 0.005) and higher serum IGFBP2 levels (HR: 3.749, P = 0.034) were independent prognostic factors predicting worse overall survival in patients with gastric cancer." (PMID 28036255, 2017). "At an optimal cut-off of 400.01 ng/ml, the sensitivity and specificity using serum IGFBP2 alone to differentiate the gastric cancer patients and healthy individuals were 79.7% and 64.7%, respectively." (PMID 28036255, 2017). "Multivariate Cox analysis showed that higher serum IGFBP2 level (> 400.01 ng/ml) was an independent prognostic factor predicting worse overall survival in patients with gastric cancer (hazard ratio (HR): 3.749, P = 0.034)." (PMID 28036255, 2017). "The mean serum IGFBP2 level of gastric cancer patients was significantly higher than that of healthy controls (805.23 ± 590.56 ng/ml vs. 459.61 ± 277.01 ng/ml; P < 0.001)." (PMID 28036255, 2017). "In conclusion, circulating IGFBP2 has potential as a biomarker predicting prognosis for gastric cancer patients." (PMID 28036255, 2017). "The mean serum IGFBP2 level was significantly elevated in the gastric cancer patients compared to controls (805.23 ± 590.56 ng/ml vs. 459.61 ± 277.01 ng/ml; P < 0.001)." (PMID 28036255, 2017). "Only a recent study demonstrated that serum IGFBP2 level was elevated in gastric cancer patients (2.2-fold change) compared to age- and sex-matched healthy controls, using a quantitative proteomic approach." (PMID 28036255, 2017). "In the present study, we tested the serum IGFBP2 levels in healthy controls and gastric cancer patients." (PMID 28036255, 2017). "Large prospective studies are required to confirm the role of IGFBP2 as a promising tumor marker in patients with gastric cancer." (PMID 28036255, 2017). "Then, based on TCGA-STAD database, we investigated the expression levels of m6A regulators’ mRNA between gastric cancer and normal samples, and discovered that compared to normal gastric tissues, 22 m6A regulators except IGFBP2 showed higher expression in tumor tissues." (PMID 38206646, 2024). "The expression of IGFBP2 in matched normal tissues is higher than that in gastric cancer tissues." (PMID 37088808, 2023). "Immunohistochemistry validated a marked downregulation of IGFBP2 protein in gastric cancer tissues." (PMID 37088808, 2023). "Besides, the IHC staining further confirmed the low expression of IGFBP2 protein in gastric cancer tissues." (PMID 37088808, 2023).
gastric cancer (continued). "In conclusion, we demonstrate significantly elevated serological levels of IGFBP2 proportional to the tumor size and stage in gastric cancer patients, and show that high serum IGFBP2 level is an independent prognostic factor predicting poor survival in patients with gastric cancer." (PMID 28036255, 2017). "Serum IGFBP2 levels were significantly increased in patients with gastric cancer." (PMID 28036255, 2017). "Since serum IGFBP2 is correlated with tumor size, clinical stage, and prognosis with relatively high sensitivity and specificity, IGFBP2 may be a good candidate biomarker for gastric cancer patients." (PMID 28036255, 2017). "We also found that PITX2 facilitated or repressed the lysosomal exocytosis of many SASP proteins, including MMP2, IGFBP2, and TIMP2, in senescent gastric cancer cells." (PMID 40995693, 2025). "Therefore, circulating IGFBP2 may become a good candidate biomarker for gastric cancer patients." (PMID 28036255, 2017). "A study of 11 gastric cancer cell lines demonstrated that IGFBP1 expression levels were extremely low in all cell lines, whereas IGFBP2 and IGFBP4 were expressed in 10 and 9 cell lines, respectively, and IGFBP3, IGFBP5, and IGFBP6 were expressed in half of all cell lines." (PMID 34745945, 2021). "Although a few previous studies suggested the prognostic role of tissue IGFBP2 in gastric cancers, the clinicopathologic and prognostic implications of circulating IGFBP2 have never been investigated in gastric cancer." (PMID 28036255, 2017). "However, the clinicopathologic and prognostic implications of circulating IGFBP2 have never been investigated in gastric cancer." (PMID 28036255, 2017).
lupus nephritis (8 papers, 2018 to 2025). Glomerulonephritis in the context of systemic lupus erythematosus. "Later validation studies using a larger study population confirmed the role of IGFBP2 as a diagnostic biomarker for SLE as well as lupus nephritis." (PMID 30214426, 2018). "In basic studies, the increased expression of IGFBP-2 in the outer cortical glomerulus may be associated with glomerular sclerosis and renal loss in lupus nephritis, and it may inhibit the mesangial proliferation induced by IGF-1 and enhance the extracellular matrix deposition." (PMID 35002740, 2021). "Previous studies reported that serum IGFBP2 levels were elevated in patients with kidney diseases including lupus nephritis and diabetic nephropathy." (PMID 33641616, 2021). "Additionally, patients with lupus nephritis, diabetic nephropathy, and chronic kidney disease have been shown to have elevated serum IGFBP-2 levels." (PMID 40231291, 2025). "Moreover, patients with lupus nephritis, diabetic nephropathy, and chronic kidney disease have been shown to have elevated serum IGFBP-2 levels." (PMID 40231291, 2025). "Clinical studies found that serum IGFBP-2 is increased in lupus nephritis (LN), but there is controversy in whether IGFBP-2 is related to renal function." (PMID 35002740, 2021). "Moreover, IGFBP2 is a potential disease monitoring biomarker for renal function and renal histopathologic changes in lupus nephritis." (PMID 30214426, 2018). "IGFBP2 has been identified as a biomarker of SLE and lupus nephritis." (PMID 35197962, 2021).
lymph node metastasis (8 papers, 2013 to 2025). "IGFBP-2 expression combined with cell adhesion protein, β-catenin, is linked with lymph node metastasis in BCs and high levels of IGFBP-2 expression together with loss of PTEN expression are also associated with triple negative (TN) BC and poor survival rates." (PMID 27050076, 2016). "However our data shows a significant positive correlation of IGFBP2 and β-catenin in lymph node metastasis." (PMID 23767917, 2013). "In addition, more lymph node metastasis was observed in patients positive for both IGFBP2 and β-catenin proteins (18/24, 75%) compared with patients with low levels of both proteins (1/24, 4%) (p = 0.0006)." (PMID 23767917, 2013). "Similarly for patients with lymph node metastasis we identified four proteins, namely IL1α, XIAP, STX2, and SHKBP1, whereas for patients with liver metastasis we identified IGF1, IL1α, IGFBP2, MAML3, and SHKBP1 as significant." (PMID 24282616, 2013).
pulmonary arterial hypertension (8 papers, 2020 to 2025). Pulmonary arterial hypertension (PAH) is a group of diseases characterized by mean pulmonary artery pressure >20 mmHg and elevated pulmonary arterial resistance leading to right heart failure. "As the second most abundant protein of this family, IGFBP-2 plays critical roles in several pathological processes including carcinogenesis, pulmonary arterial hypertension (PAH), obesity and insulin resistance." (PMID 36970368, 2023). "In pulmonary hypertension, in addition to their IGF-dependent signaling, IGFBP-1 and IGFBP-2 have an IGF-1R-independent kinase activation pattern in smooth muscle cells, and IGFBP-2 induces EGFR and STAT3 signaling." (PMID 41226289, 2025). "Serum IGFBP2 levels, as well as IGF1/2 levels, were measured in two independent PAH cohorts, the Johns Hopkins Pulmonary Hypertension program (JHPH, N = 127), NHLBI PAHBiobank (PAHB, N = 203), and a healthy control cohort (N = 128)." (PMID 33019943, 2020). "Furthermore, significantly reduced expression of IGFBP2 was evident in AEC2 cells of patients with IPF and/or IPF with pulmonary arterial hypertension." (PMID 40121473, 2025).
Sepsis (8 papers, 2014 to 2025). Sepsis is defined as life-threatening organ dysfunction caused by a dysregulated host response to infection. "In this study, we investigated the ability of insulin-like growth factor-binding protein-2 (IGFBP-2) in the IGF pathway to predict kidney injury caused by sepsis, enabling early detection and intervention." (PMID 40231291, 2025). "Elevated plasma IGFBP-2 levels have been consistently associated with CI, particularly in conditions such as sepsis and acute respiratory distress syndrome (ARDS)." (PMID 39585162, 2024). "Plasma IGFBP-2 levels in COVID-19 patients were higher compared to healthy controls but were similar to those with SIRS/sepsis from other causes." (PMID 38137505, 2023). "The clinical importance of IGFBP-2 is emphasized by its correlation with disease severity in conditions like sepsis and coronavirus disease 2019 (COVID-19), where its levels are markedly elevated compared to healthy controls and are similar to those observed in sepsis from various causes." (PMID 39585162, 2024). "Our study revealed that sepsis patients with higher plasma IGFBP-2 levels have a significantly greater probability of developing SA-AKI than do those with lower IGFBP-2 levels." (PMID 40231291, 2025). "Overall, elevated IGFBP-2 levels in sepsis and COVID-19 point to its potential as a marker for disease severity and mortality risk." (PMID 39585162, 2024). "The course of IGFBP-2 in CI, particularly in the contexts of sepsis andCOVID-19, points to its significant role as a biomarker of disease severity." (PMID 39585162, 2024). "The significance of IGFBP-2 in the pathophysiology of CI, particularly in sepsis and COVID-19, is increasingly recognized." (PMID 39585162, 2024). "While higher IGFBP-2 levels in patients with kidney disease have been reported, this study—for the first time—analyzes IGFBP-2 in renal failure related to sepsis." (PMID 38255230, 2024). "In conclusion, our study indicates that plasma IGFBP-2 levels are associated with disease severity, renal failure, and mortality in SIRS/sepsis patients." (PMID 38137505, 2023). "The AUROC of IGFBP-2 for sepsis diagnosis described in this study was 0.90 (sensitivity 77%, specificity 91%)." (PMID 38137505, 2023). "Our analysis of 157 SIRS/sepsis patients revealed higher plasma IGFBP-2 levels compared to 22 healthy controls." (PMID 38137505, 2023). "Our study aimed to evaluate the associations between plasma IGFBP-2 levels and disease severity and outcome in SIRS/sepsis patients." (PMID 38137505, 2023). "Insulin-like growth factor-binding protein (IGFBP)-2 regulates the bioactivity of the anabolic hormone’s insulin-like growth factors, which are decreased in sepsis and contribute to the catabolic status of severely ill patients." (PMID 38137505, 2023). "A dysfunctional immune system characterizes sepsis, yet the role of IGFBP-2 in critical illness remains understudied." (PMID 38137505, 2023). "The current study reveals that SIRS/sepsis patients exhibit higher plasma IGFBP-2 levels than healthy controls." (PMID 38137505, 2023). "Urosepsis, commonly caused by enterobacteria and Gram-positive bacteria, resulted in IGFBP-2 levels similar to other SIRS/sepsis patients." (PMID 38137505, 2023). "A plasma level of 232 ng/mL IGFBP-2 discriminated SIRS/sepsis patients from controls, with 77% sensitivity and 91% specificity." (PMID 38137505, 2023). "This study revealed that plasma IGFBP-2 levels in SIRS/sepsis patients are over three times higher than in healthy controls." (PMID 38137505, 2023). "Both men and women in the control and SIRS/sepsis groups had comparable IGFBP-2 levels (p = 0.056 and 0.903, respectively)." (PMID 38137505, 2023). "IGFBP-2 may have a complex mechanism in the process of SA-AKI in sepsis patients, but these mechanisms are not yet well understood." (PMID 40231291, 2025). "Some studies have suggested that the severity of sepsis itself may influence the expression of plasma IGFBP-2." (PMID 40231291, 2025).
Sepsis (continued). "Therefore, the increase in IGFBP-2 is more related to the progression of sepsis itself than to infection." (PMID 40231291, 2025). "IGFBP-2 levels can predict the occurrence of SA-AKI in sepsis patients." (PMID 40231291, 2025). "Research indicates that patients with systemic inflammatory response syndrome (SIRS) or sepsis exhibit markedly elevated IGFBP-2 levels compared to healthy controls, with these elevations correlating with the need for dialysis, disease severity, and ultimately mortality." (PMID 39585162, 2024). "Elevated IGFBP-2 levels in sepsis and COVID-19 patients compared to other CI etiologies could aid in differential diagnosis." (PMID 39585162, 2024). "Plasma IGFBP-2 positively correlated with procalcitonin levels in the SIRS/sepsis cohort." (PMID 38137505, 2023). "The further blockage of IGF activity by elevated IGFBP-2 levels in SIRS/sepsis—as shown in our study—might intensify these catabolic processes, leading to sarcopenia and cachexia." (PMID 38137505, 2023). "Furthermore, in the SIRS/sepsis cohort, elevated plasma IGFBP-2 was observed in septic shock patients, those requiring dialysis, and non-survivors." (PMID 38137505, 2023). "Immune suppression accounts for most sepsis-related deaths and IGFBP-2 may become a therapeutic target." (PMID 38137505, 2023). "Since the CRP and procalcitonin levels remained consistent across patients with SIRS, sepsis, or septic shock, IGFBP-2 may be a superior marker." (PMID 38137505, 2023). "In the SIRS/sepsis cohort, plasma IGFBP-2 positively correlated with procalcitonin." (PMID 38137505, 2023). "The plasma IGFBP-2 concentrations of 157 patients with SIRS/sepsis were measured." (PMID 38137505, 2023). "In these situations, biomarkers like IGFBP-2 or mid-regional pro-adrenomedullin levels (MR-proADM) could confirm sepsis." (PMID 38137505, 2023). "Blocking IGFBP-2 activity may improve the catabolic status in sepsis and may also boost the immune response because of the immunosuppressive effects of IGFBP-2." (PMID 38137505, 2023). "However, comparing septic shock patients with and without dialysis showed similar plasma IGFBP-2 levels, and the role of plasma IGFBP-2 as a marker of kidney injury in sepsis needs to be studied further." (PMID 38137505, 2023). "In addition, IGFBP2 has been proven to be upregulated in patients with sepsis and mice with high-dose nandrolone-induced septic shock, consistent with our study." (PMID 36781867, 2023). "This study aimed to explore whether plasma IGFBP-2 levels can predict the occurrence of septic kidney injury in critically ill patients by analysing the relationship between plasma IGFBP-2 levels and the development of sepsis-induced kidney injury within 48 hours." (PMID 40231291, 2025). "IGFBP1, IGFBP2, IGF2BP1, and WTAP were highly expressed in advanced sepsis patients, and the remaining 17 regulators were poorly expressed." (PMID 37330481, 2023). "Peripheral immune cells from patients with severe sepsis express higher levels of IGFBP-2 than those from healthy controls, suggesting a potential involvement of IGFBP-2 in immune cell dysfunction." (PMID 38137505, 2023). "Based on the RF model and correlation analysis, IGFBP1, IGFBP2, IGF2BP1, WTAP, and METTL16 were screened out to accelerate the occurrence and development of sepsis by regulating m6A methylation and promoting immune cell infiltration." (PMID 37330481, 2023). "We measured IGFBP-2 in the plasma of 157 critically ill patients with systemic inflammatory syndrome (SIRS), sepsis, or septic shock." (PMID 38137505, 2023). "The results showed that IGFBP1, IGFBP2, IGF2BP1, and WTAP were highly expressed in patients with advanced sepsis and m6A cluster B; IGFBP1, IGFBP2, and IGF2BP1 showed a significant positive correlation with Th17 helper T cells." (PMID 37330481, 2023).
Sepsis (continued). "IGFBP1, IGFBP2, IGF2BP1, and WTAP were highly expressed in patients with advanced sepsis and m6A cluster B. IGFBP1, IGFBP2, and IGF2BP1 were positively correlated with Th17 helper T cells." (PMID 37330481, 2023). "Patients on dialysis, all experiencing acute kidney failure due to sepsis, had higher serum IGFBP-2 levels compared to those not undergoing dialysis." (PMID 38255230, 2024). "In our study, the 24 septic COVID-19 patients exhibited plasma IGFBP-2 levels comparable to the SIRS/sepsis patients without a SARS-CoV-2 infection (p = 0.606)." (PMID 38137505, 2023). "The plasma IGFBP-2 levels of patients surviving SIRS/sepsis were lower in comparison to non-survivors." (PMID 38137505, 2023). "The circulating levels of IGFBP-2 in critical illness have been rarely studied; therefore, we evaluated IGFBP-2 plasma levels in patients with systemic inflammatory response syndrome (SIRS) or sepsis as well as healthy controls." (PMID 38137505, 2023). "IGFBP1, IGFBP2, IGF2BP1, WTAP, and METTL16 may accelerate the development of advanced sepsis by regulating m6A methylation modification and promoting immune cell infiltration." (PMID 37330481, 2023). "While IGFBP-2 is being considered as a potential tumor marker, the 14 patients in our SIRS/sepsis group with various cancers had IGFBP-2 levels similar to those without tumors (p = 0.796)." (PMID 38137505, 2023). "Septicemia due to sepsis does not seem to alter plasma IGFBP-2 levels, and sheep injected with lipopolysaccharide maintained normal IGFBP-2 levels throughout the nine-hour observation period." (PMID 40231291, 2025).
aortic stenosis (7 papers, 2020 to 2025). Aortic valve stenosis is a aortic valve disease caused by the incomplete opening of the aortic valve. "Low levels of IGFBP2 are independently associated with a lower stroke volume index, which is a powerful predictor of poor prognosis in patients with aortic stenosis." (PMID 33329019, 2020). "In addition to strongly predicting mortality in HF patients, IGFBP-2 has recently emerged as a novel candidate biomarker for cardiovascular risk assessment in patients with aortic stenosis who undergo transcatheter aortic valve implantation and elderly men." (PMID 36970368, 2023). "Prior studies reported that IGFBP-2 independently predicts for adverse clinical outcomes in patients with HF, severe aortic stenosis, dilated cardiomyopathy and PAH." (PMID 36970368, 2023). "Plasma IGFBP-2 was associated with cardiovascular mortality in acute and chronic heart failure patients, and serum IGFBP-2 levels predicted mortality in patients with severe aortic stenosis." (PMID 38255230, 2024). "The highest quartile of plasma IGFBP-2 correlated with cardiovascular mortality in both acute and chronic heart failure patients, and serum IGFBP-2 levels exceeding 275 ng/mL predicted mortality in patients with severe aortic stenosis." (PMID 38137505, 2023).